CUL5 (cullin 5)
Diseases named in the same sentence as CUL5 in open-access papers (continued):
Sharing a sentence is not in itself a finding about the gene and the disease.
CUL5 also shares sentences with these, for which no sentence is quoted: atherosclerosis (4 papers); infection (4); Hypertension (3); pancreatic cancer (3); renal cell carcinoma (2); Stroke (2); Allergy (1); Alzheimer disease (1); Arrhythmia (1); arteriosclerosis (1); atrial fibrillation (1); bladder urothelial carcinoma (1); cervical squamous cell carcinoma (1); cholangiocarcinoma (1); clear renal cell carcinoma (1); Coats disease (1); colon cancer (1); COVID-19 (1); dementia (1); endocervical adenocarcinoma (1); endometrial adenocarcinoma (1); endothelial dysfunction (1); esophageal carcinoma (1); heart failure (1); hematological diseases (1); Hirschsprung disease (1); ischaemic heart disease (1); leukemia (1); lung adenocarcinoma (1); melanoma (1).
A further 9 diseases each share a sentence with CUL5 in 1 paper.